RPL10 (ribosomal protein L10)
Diseases named in the same sentence as RPL10 in open-access papers (continued):
Sharing a sentence is not in itself a finding about the gene and the disease.
infection (11 papers, 2012 to 2025). The state of being infected such as from the introduction of a foreign agent such as serum, vaccine, antigenic substance or organism. "Consistent with an RPL10 role in antiviral defense, loss of RPL10 function recapitulated the nik1 enhanced susceptibility phenotype to begomovirus infection, as the rpl10 knockout lines developed similar severe symptoms and displayed similar infection rate as nik1." (PMID 28199446, 2017). "Consistent with a role for RPL10 in antiviral defense, loss of RPL10 function recapitulates the nik1 enhanced susceptibility phenotype to begomovirus infection, as rpl10 knockout lines develop severe symptoms similar to those of nik1 and display a similar infection rate." (PMID 28105028, 2016). "RPL10 was significantly activated upon infection with Xoo pathogen, whereas among the RPS genes, RPS4 became commonly up-regulated under both Xoo and R. solani treatments." (PMID 28966624, 2017). "Among those that were expressive (RPL10, 11, 15, 24a, 26, 27, and 37), the expression of RPL10 was more evident as its transcript levels gradually increased from 3 h post-infection and reached a peak at 11 days after treatment." (PMID 27605933, 2016). "In addition to significant expression at 11 days, the transcript level of RPL10 also exhibited a gradual increase at 3 h, 6 h, 1 day, and 2 days up to 7 days post-infection with the Xanthomonas oryzae pv." (PMID 27605933, 2016).
neurodevelopmental disorder (6 papers, 2014 to 2025). A behavioral and cognitive disorder with onset during the developmental period that involves impaired or aberrant development of intellectual, motor, or social functions. "RPL10, located on the Xq28 chromosome, has an essential function in ribosome assembly and protein translation, and it is associated with neurodevelopmental disorders." (PMID 33718354, 2021). "It is notable the EJC downstream splicing changes include several genes, such as RPL10, which are mutated in patients with neurodevelopmental disorders." (PMID 27618312, 2016). "The close neighborhood of the RPL10 protein to both proteins in the energy metabolism co-expression network may thus underscore the etiological relevance of RPL10 in neurodevelopmental disorders." (PMID 24512814, 2014).
bacterial infection (1 paper, 2022). "RPL10 play a vital role during both viral and bacterial infection acting as a positive and negative regulator." (PMID 35850621, 2022).
hematologic malignancy (1 paper, 2023). "Whereas the higher expression of RPL10 is reported to be associated with poor prognosis mainly in hematologic malignancy, its relation to prognosis in breast malignancy has not been fully investigated." (PMID 37231433, 2023).
hematological cancer (1 paper, 2022). "The RPL10‐R98S mutation was originally identified in a human hematological cancer." (PMID 35140557, 2022).
inherited disease (1 paper, 2020). "This may be the case also for a few inherited diseases or disorders, described in the past 15 years, all of which are attributed to mutations in RPL10." (PMID 33227977, 2020).
RPL10 also shares sentences with these, for which no sentence is quoted: glioblastoma (2 papers); acute myeloid leukemia (1); adult T-cell acute lymphoblastic leukemia (1); Aphasia (1); Ataxia (1); chronic lymphocytic leukemia (1); clear cell sarcoma of the kidney (1); endometrial cancer (1); glioma (1); HCMV infection (1); intellectual impairment (1); lymphoma (1); myelodysplastic syndrome (1); neuroferritinopathy (1); osteosarcoma (1); Parkinson’s (1); Seizure (1); teratoma (1).